SIK1 (salt inducible kinase 1)
Diseases named in the same sentence as SIK1 in open-access papers (continued):
Sharing a sentence is not in itself a finding about the gene and the disease.
Insulin resistance (5 papers, 2017 to 2024). Increased resistance towards insulin, that is, diminished effectiveness of insulin in reducing blood glucose levels. "Previous studies have demonstrated that Sik1 is upregulated in skeletal muscle, liver and adipose tissue of obese mice and this has been linked to the development of insulin resistance." (PMID 27807598, 2017). "Additionally, SIK1 has been shown to take part in hepatocyte ROS production in hyperinsulinemia-induced insulin resistance." (PMID 39546296, 2024). "Interestingly, global Sik1 knockout mice are protected against high-fat diet induced insulin resistance." (PMID 39081779, 2024). "The DEGs and DELs between the QGL and MOD groups, such as TG, SIK1, PPP1R3C, CRTC2, PGC-1α, G6PC, PPP1R3G, and SREBP1 were found to be relevant to insulin resistance." (PMID 36452137, 2022). "In addition to modulating gluconeogenesis and insulin resistance and thus indirectly influencing SREBP1 activity, both SIK1 and PPP1R3C can directly regulate SREBP1 expression." (PMID 36452137, 2022). "Our research indicated that QGD may improve insulin resistance via regulating the expression of CRTC2, SIK1, PPP1R3C, PGC-1α, G6PC, PPP1R3G, and SREBP1, which are involved in gluconeogenesis." (PMID 36452137, 2022). "Sik1 deletion in skeletal muscle, but not liver or adipose tissue phenocopies the whole-body knockout mice, suggesting skeletal muscle Sik1 contribute to diet-induced insulin resistance through a tissue autonomous mechanism." (PMID 39081779, 2024).
cardiac hypertrophy (4 papers, 2012 to 2024). "A polymorphism in SIK1 gene encoding a G15S missense mutation is associated with lower blood pressure and reduced cardiac hypertrophy in humans." (PMID 39081779, 2024). "Cardiac hypertrophy of the spontaneous hypertensive rats is associated with decreased cardiac expression of SIK1 and SIK3." (PMID 39081779, 2024). "Up-regulated genes bound by TWIST1 included the two pore channel Tpcn1; the Rho activating protein, Abra, which has been implicated in cardiac hypertrophy; the kinase Sik1; and the uncharacterized genes Gatsl2 and Wdr75." (PMID 22815831, 2012). "Therefore, the loss of SIK1 should lead to decreased Na+-K+-ATPase activity, and accordingly, Sik1 knockout (KO) mice on a high-salt diet developed higher systolic blood pressure and cardiac hypertrophy and also showed hypertensive phenotypes." (PMID 36731029, 2023). "While global sik1−/− mice exhibit a similar blood pressure to sik1+/+ mice under normal salt conditions, during chronic high salt intake (1% NaCl), the mice exhibit high systolic blood pressure and signs of cardiac hypertrophy." (PMID 30021947, 2018). "Increases in intracellular sodium activates SIK1 and increases MEF2 transcriptional activity and cardiac hypertrophy signature gene expression in myocardial cells." (PMID 39081779, 2024). "SIK1 and SIK2 play distinct roles in mediating the HS-induced high BP and cardiac hypertrophy in mouse models." (PMID 39081779, 2024). "Instead, combined Sik1/2 deletion leads to higher BP but does not alter LVH on chronic HS intake, suggesting that SIK1 is required for maintaining normal BP while SIK2 is required for HS-induced cardiac hypertrophy independent of high BP." (PMID 39081779, 2024). "On HS condition, Sik1 deletion leads to increased BP and vascular remodeling, as indicated by higher systolic BP, upregulation of TGFβ1 signaling, increased expression of endothelin-1 and genes related to VSMC contraction, and signs of cardiac hypertrophy." (PMID 39081779, 2024). "Unlike the pro-hypertrophic role of SIK1, SIK3 functions as a suppressor of cardiac hypertrophy." (PMID 39081779, 2024).
colorectal cancer (4 papers, 2020 to 2023). A primary or metastatic malignant neoplasm that affects the colon or rectum. "In the present study, we investigated the role of salt-induced kinase 1 (SIK1), a serine/threonine kinase protein, in colorectal cancer (CRC)." (PMID 37670972, 2023). "SIK1 can suppress colorectal cancer metastasis and oxaliplatin resistance via TGF-β signaling pathway-mediated EMT." (PMID 37670972, 2023). "In addition, TCGA database analysis showed that SIK1 promoter methylation level was significantly increased in colorectal cancer tissues." (PMID 37670972, 2023).
type 2 diabetes mellitus (4 papers, 2019 to 2023). A type of diabetes mellitus that is characterized by insulin resistance or desensitization and increased blood glucose levels. "Moreover, our previous study suggested that high-glucose stimulation could reduce both protein and mRNA levels of SIK1 in rat HBZY-1 cells; in addition, SIK1 expression was also low in type 2 diabetic rat liver." (PMID 33013689, 2020). "In this study, we investigated the role and mechanism of Salt-induced kinase 1 (SIK1) in regulation of hepatic glucose and lipid metabolism in a high-fat food (HFD) and streptozocin (STZ)-induced type 2 diabetes mellitus (T2DM) rat model." (PMID 31233505, 2019).
fatty liver (3 papers, 2019 to 2022). "SIK1 overexpression in the liver relieved hyperglycemia, hyperlipidemia and fatty liver." (PMID 32020874, 2020). "In the present study, we generates a diabetic rat model treated with HFD plus low-dose STZ and focuses on the role of SIK1 in the hepatic gluconeogenic and lipogenic pathways and their effect on the resulting phenotype of lower fasting glucose levels and ameliorated fatty liver disease." (PMID 31233505, 2019). "An interaction network based on DELs and differential genes (DEGs) suggested that QGD inhibited hepatic steatosis mainly by reducing hepatic insulin resistance and triglyceride biosynthesis via the PPP1R3C/SIK1/CRTC2 and PPP1R3C/SIK1/SREBP1 signal axis, respectively." (PMID 36452137, 2022).
Hyperglycemia (3 papers, 2019 to 2023). An increased concentration of glucose in the blood. "This is obviously the first report that suggests the potential of adenovirus-mediated SIK1 gene transfer in the management of hyperglycaemia in the HFD/STZ-induced T2DM rat model." (PMID 31233505, 2019). "Overexpression of SIK1 ameliorates hyperglycaemia and fatty liver by suppressing hepatic gluconeogenesis and lipogenesis in HFD/STZ-induced T2DM rats." (PMID 31233505, 2019). "Furthermore, SIK1 knockdown in mice induced gluconeogenic gene expression and fasting hyperglycemia." (PMID 36731029, 2023). "To determine whether SIK1 overexpression ameliorates hyperglycaemia by decreasing endogenous glucose production in the liver, we measured the mRNA and protein of SIK1, CRTC2, PEPCK and G6pase in the liver." (PMID 31233505, 2019). "Three rats died of hyperglycemia in the DM and Ad-GFP groups, while two rats died of hyperglycemia in the Ad-SIK1 and Met groups, respectively, and one rat died of hyperglycemia in the ZQR group." (PMID 32020874, 2020). "Therefore, the SIK1/CRTC2 signalling pathway will probably represent a novel strategy for suppressing hepatic gluconeogenesis and ameliorating hyperglycaemia." (PMID 31233505, 2019). "In the present study, the administration of Ad-SIK1 resulted in amelioration of hyperglycaemia in HFD/STZ-induced diabetic rats, suggesting that exogenous SIK1 might have a protective effect on T2DM." (PMID 31233505, 2019). "Additionally, metformin, a widely used hypoglycemic drug, which attenuated hyperglycaemia and NAFLD in HFD/STZ-induced diabetic rats, increased SIK1 expression levels in HepG2 cells cultured in high glucose conditions." (PMID 31233505, 2019). "Indeed, SIK1 KO mice on a high-fat diet do not exhibit hyperglycemia or increased gluconeogenesis but display pronounced improvement in peripheral insulin sensitivity, glucose tolerance, and skeletal muscle glucose uptake as a result of upregulation of GLUT1, GLUT4, and GLUT12 expression." (PMID 36731029, 2023).
medulloblastoma (3 papers, 2020 to 2024). A malignant, invasive embryonal neoplasm arising from the cerebellum.
melanoma (3 papers, 2011 to 2021). A malignant, usually aggressive tumor composed of atypical, neoplastic melanocytes. "GSK-3 beta is capable of phosphorylating (activating) sites in the activation loop of SIK1/2, and the activated SIK1/2 proteins are stable, suggesting that B16F10 melanoma cells that have been treated with GSK-3 beta inhibitors have low levels of SIK2, which would promote melanogenesis." (PMID 22022544, 2011).
pancreatic cancer (3 papers, 2020 to 2023). "It has been reported that pancreatic cancer cells with SIK1 knockdown expression are more likely to invade and metastasize and are related to the regulation of microRNA-203 (miR-203)." (PMID 37670972, 2023).
steatosis (3 papers, 2019 to 2023). Increased lipid within the cytoplasm of cells. "In conclusion, the present study revealed that SIK1 inhibits hepatic gluconeogenesis and steatosis and that proper regulation of CRTC2 activity by SIK1 kinase is essential for suppressing abnormal hepatic glucose production and lipid storage." (PMID 32020874, 2020). "As expected, Ad-SIK1 administration significantly inhibited hepatic gluconeogenesis and steatosis in diabetic rats." (PMID 32020874, 2020). "SIK1 reduces the expression of lipogenic enzymes, diminishing steatosis." (PMID 36978847, 2023). "Thus, Ad-SIK1 treatment significantly reduced fat deposition compared with the DM group, indicating that Ad-SIK1 administration could markedly improve steatosis." (PMID 31233505, 2019).
adrenocortical tumor (2 papers, 2020 to 2024). "Early studies showed that Ser577 autophosphorylation led to the nuclear export of SIK1 in mouse adrenocortical tumor cells, and mutation at this site resulted in SIK1 retention in the nucleus." (PMID 33013689, 2020). "On the contrary, SIK1 is highly expressed in adrenocortical tumor cells of Y1 mice stimulated by adrenocorticotropic hormone." (PMID 39063214, 2024).
autism (2 papers, 2021 to 2024). Persistent deficits in social interaction and communication and interaction as well as a markedly restricted repertoire of activity and interest as well as repetitive patterns of behavior. "Social deficits and language problems are the common symptoms of autism and are also reported in human cases with SIK1 mutation." (PMID 34295222, 2021). "Out of these patients with autism, two had missense mutations and the other two had nonsense mutations within NLD-coding exon, resulting in the C-terminal truncation of the SIK1 protein." (PMID 34295222, 2021). "Regulatory inference using the Genie3 algorithm identified direct regulation of IGF1 by SIK1, MFRP, CHD7, NIPBL, EXOC5, and ARID2, with SIK1 and SPARCL1 significantly downregulated in autism brain organoids, potentially affecting IGF1 expression." (PMID 39376742, 2024).
colon cancer (2 papers, 2020 to 2023). "In summary, SIK1 can act as a tumor suppressor in colon cancer by inhibiting the TGF-β pathway." (PMID 37670972, 2023).
Down syndrome (2 papers, 2010 to 2023). "Given that sik1 is specifically involved in cardiomyogenesis, we can speculate that this gene can play a role in CHDs observed in Down syndrome patients, opening new avenues in the understanding of the biological pathways involved in this severe disorder." (PMID 20140255, 2010).
epileptic encephalopathies (2 papers, 2017 to 2025). "Pathogenic SIK1 variants are most often described in early-onset epileptic encephalopathy, though later-onset cases with broader neurodevelopmental impairment and behavioral features are also briefly mentioned in the literature but remain poorly characterized." (PMID 41040937, 2025). "Defects in salt-inducible kinase 1 (SIK1), encoding a serine/threonine protein kinase implicated in signal transduction, cause a spectrum of epileptic encephalopathies including early myoclonic encephalopathy, IS, and Ohtahara syndrome (OS)." (PMID 28649286, 2017). "Out of six individuals with epileptic encephalopathies (early myoclonic encephalopathy, OS, and IS) due to SIK1 variants, three developed features of ASD in the context of experiencing IS between 2–4 months of age." (PMID 28649286, 2017).
gastric adenocarcinoma (2 papers, 2014 to 2018). "In the present study we show that gastrin induces transient SIK1 expression in pancreatic and gastric adenocarcinoma cells, and that the gastrin-induced SIK1 expression is negatively regulated by Inducible cAMP early repressor (ICER)." (PMID 25384047, 2014). "Evidence provided here demonstrates that SIK1 is regulated by gastrin and influences gastrin elicited signalling in gastric adenocarcinoma cells." (PMID 25384047, 2014). "Next we find that siRNA mediated knockdown of SIK1 increases migration of the gastric adenocarcinoma cell line AGS-GR." (PMID 25384047, 2014). "We show that SIK1 knockdown by siRNA brings along higher migratory activity in gastric adenocarcinoma cells, indicating that SIK1 suppresses gastrin-mediated migration." (PMID 25384047, 2014). "Collectively, this suggests a role of SIK1 in gastrin induced responses and suggest that SIK1 may act as tumour suppressor in gastric adenocarcinoma cells." (PMID 25384047, 2014). "To conclude, in this study we characterize a function of SIK1 in gastric adenocarcinoma cells." (PMID 25384047, 2014). "In gastric adenocarcinoma AGS-GR cells, the SIK1 mRNA was peaking at 1 h." (PMID 25384047, 2014).
gastric cancer (2 papers, 2014 to 2022). A primary or metastatic malignant neoplasm involving the stomach. "Since cell migration and invasion are characteristics of the progression of gastric cancer, and processes known to be regulated by gastrin, we wanted to address the role of SIK1 in gastrin-mediated responses." (PMID 25384047, 2014). "To investigate whether SIK1 participates in regulation of the CRTC2-CREB axis also in gastric cancer cells, we examined the subcellular localization of CRTC2 protein upon gastrin treatment in AGS-GR cells." (PMID 25384047, 2014).
glucose metabolism disorders (2 papers, 2019 to 2020). "Previous studies showed that the signaling pathways mediated by SIK1 play critical functions in glucose metabolism disorders." (PMID 33013689, 2020). "Recently, salt-inducible kinase 1 (SIK1) has been identified to play an important role in glucose metabolism disorders, but whether and how SIK1 regulates the CTRC2 signaling in liver cells under high glucose conditions has rarely been intensively elucidated." (PMID 33013689, 2020).
infantile epileptic encephalopathy (2 papers, 2021). an epileptic condition characterized by epileptiform abnormalities associated with progressive cerebral dysfunction. "Six mutations in the salt-inducible kinase 1 (SIK1)-coding gene have been identified in patients with early infantile epileptic encephalopathy (EIEE-30) accompanied by autistic symptoms." (PMID 34295222, 2021). "Six mutations in the SIK1 gene were identified in the patients with early infantile epileptic encephalopathy (EIEE-30)." (PMID 34295222, 2021).
non-alcoholic fatty liver disease (2 papers, 2020 to 2024). "This technology has been used to silence genes crucial for adipocyte differentiation, such as PPARG and FKBP5, as well as to target three genes (SOCS3, DUSP1, and SIK1) that are upregulated in the adipose tissue of patients with nonalcoholic fatty liver disease (NAFLD)." (PMID 39684387, 2024).
triple-negative breast carcinoma (2 papers, 2020 to 2023). An invasive breast carcinoma which is negative for expression of estrogen receptor (ER), progesterone receptor (PR), and human epidermal growth factor receptor 2 (HER2). "Double knockouts of SIK1 and SIK3 increase triple-negative breast cancer invasion, which agrees with the finding that SIK1 and SIK3 are involved in LKB1-mediated tumor suppression pathways." (PMID 36731029, 2023). "Indeed, in triple-negative breast cancer tissues, SIK3 is highly expressed while SIK1 and SIK2 are reduced." (PMID 36731029, 2023).
adenovirus infection (1 paper, 2020). "Using a SIKs inhibitor and plasmid transfection- or adenovirus infection-mediated ectopic expression of SIK1 in liver cells, SIK1's impacts on the cellular location and expression levels of hepatic gluconeogenesis-associated key molecules were assessed." (PMID 33013689, 2020). "Interestingly, ad-SIK1 adenovirus infection led to significantly increased SIK mRNA expression in mouse liver cells in comparison with un-infected and control virus-infected cells but resulted in largely unaltered protein expression of SIK1." (PMID 33013689, 2020).
Allergy (1 paper, 2024). An allergy is an immune response or reaction to substances that are usually not harmful. "Conversely, the allergy-associated SNP rs7380290 is accessible and contacts the SIK1 promoter in resting cells, but shows reduced accessibility and promoter connectivity upon activation." (PMID 39302339, 2024).
Anxiety (1 paper, 2021). Intense feelings of nervousness, tension, or panic often arise in response to interpersonal stresses. "There was no change in movement in the elevated plus maze, which also suggests that the anxiety level was unchanged in SIK1-MT mice." (PMID 34295222, 2021).
asthma (1 paper, 2025). "In this study, using machine learning techniques, we identified salt-inducible kinase 1 (SIK1), which plays a crucial role in associating with the asthma phenotype and EV-D68 infection." (PMID 41674661, 2025). "Taken together, our findings suggest that SIK1 serves as a protective factor in EV-D68-induced asthma by modulating antiviral immune responses, which provide new insights into potential treatments for EV-D68-induced asthma attacks." (PMID 41674661, 2025). "Using weighted gene co-expression network analysis, we demonstrated SIK1's role in antiviral immune responses in asthma." (PMID 41674661, 2025). "Concretely, a negative correlation between SIK1 expression and asthma risk has been revealed through Mendelian randomization." (PMID 41674661, 2025). "Finally, in the asthma exacerbation model of HDM combined with EV-D68 infection, SIK1 activation effectively mitigated EV-D68-induced asthma exacerbation in mice." (PMID 41674661, 2025).
Atrophy (1 paper, 2021). Any weakening or degeneration, especially through lack of use. "HDAC4 also regulates cell division, cell cycle, apoptotic process, and cell differentiation via CDKN1A and SIK1, involving in denervation-induced muscle atrophy." (PMID 34276308, 2021). "Taken together, HDAC4 inhibition can alleviate denervation-induced muscle atrophy by reducing MYOG expression, and HDAC4 is also directly related to CDKN1A and SIK1 in skeletal muscle, which suggests that HDAC4 inhibitors may be a potential drug for the treatment of neurogenic muscle atrophy." (PMID 34276308, 2021).
autism spectrum disorder (1 paper, 2025). A spectrum of developmental disorders that includes autism, and Asperger syndrome. "Based on recent clinical exome sequencing, our current understanding is that her catatonia is secondary to a late-onset autism spectrum disorder, likely associated with a pathogenic variant in SIK1, potentially explaining her incomplete and transient response to multiple treatment regimens." (PMID 41040937, 2025).
autoimmune uveitis (1 paper, 2024). An autoimmune form of uveitis (disease). "Reduction of intraocular inflammation in experimental autoimmune uveitis through a mechanism involving phosphorylation of SIK1 has been proposed." (PMID 39546296, 2024).